IGKV1D-39 (immunoglobulin kappa variable 1D-39)
Description:
V region of the variable domain of immunoglobulin light chains that participates in the antigen recognition. Immunoglobulins, also known as antibodies, are membrane-bound or secreted glycoproteins produced by B lymphocytes. In the recognition phase of humoral immunity, the membrane-bound immunoglobulins serve as receptors which, upon binding of a specific antigen, trigger the clonal expansion and differentiation of B lymphocytes into immunoglobulins-secreting plasma cells. Secreted immunoglobulins mediate the effector phase of humoral immunity, which results in the elimination of bound antigens. The antigen binding site is formed by the variable domain of one heavy chain, together with that of its associated light chain. Thus, each immunoglobulin has two antigen binding sites with remarkable affinity for a particular antigen. The variable domains are assembled by a process called V-(D)-J rearrangement and can then be subjected to somatic hypermutations which, after exposure to antigen and selection, allow affinity maturation for a particular antigen.
Synonyms: IGKV1D39; O2
Tractability: Antibody: its Gene Ontology location is reachable by antibodies, with high confidence; UniProt places it where antibodies can reach, with medium confidence; UniProt predicts a signal peptide or a membrane-spanning region.
Gene: Immunoglobulin variable (V) gene on chromosome 2 (89,862,482 to 89,862,981, forward strand). Ensembl gene ENSG00000251546.
Subcellular location: Secreted; Cell membrane
Pathways (Reactome):
Immune System: Antigen activates B Cell Receptor (BCR) leading to generation of second messengers; CD22 mediated BCR regulation; Classical antibody-mediated complement activation; FCERI mediated Ca+2 mobilization; FCERI mediated MAPK activation; FCERI mediated NF-kB activation; FCGR activation; Fc epsilon receptor (FCERI) signaling; Immunoregulatory interactions between a Lymphoid and a non-Lymphoid cell; Initial triggering of complement; Regulation of Complement cascade; Regulation of actin dynamics for phagocytic cup formation; Role of LAT2/NTAL/LAB on calcium mobilization; Role of phospholipids in phagocytosis
Disease: FCGR3A-mediated IL10 synthesis; FCGR3A-mediated phagocytosis; Potential therapeutics for SARS
Hemostasis: Cell surface interactions at the vascular wall
Vesicle-mediated transport: Scavenging of heme from plasma
Gene Ontology:
Molecular function: antigen binding
Biological process: immune response
Cellular component: extracellular region; immunoglobulin complex; plasma membrane
Homologues: Orthologues: mouse Igkv15-103 (74% identical). Paralogues in human: IGKV1-39 (100% identical), IGKV1-12 (91% identical), IGKV1-9 (91% identical), IGKV1-6 (91% identical), IGKV1D-12 (91% identical), IGKV1D-13 (91% identical), IGKV1D-16 (90% identical), IGKV1OR2-108 (90% identical), IGKV1-16 (89% identical), IGKV1-17 (89% identical), IGKV1-27 (89% identical), IGKV1-5 (89% identical), and 81 more.
Diseases named in the same sentence as IGKV1D-39 in open-access papers:
IGKV1D-39 is named in the same sentence as 3 diseases in open-access papers, as found by Europe PMC text mining. Sharing a sentence is not in itself a finding about the gene and the disease. The quoted sentences say what the papers report.
pancreatic cancer (1 paper, 2021). "Our analyses revealed that the immune-related genes CCR4, CD19, TNFSF8, SH2D1A, ICOS, IGKV1D-39, and TNFRSF17 may be implicated in the immunophenotyping of pancreatic cancer." (PMID 34737763, 2021). "The results revealed seven immune-related genes (CCR4, CD19, TNFSF8, SH2D1A, ICOS, IGKV1D-39, and TNFRSF17) could potentially influence the immunophenotyping of pancreatic cancer." (PMID 34737763, 2021).
IGKV1D-39 also shares sentences with these, for which no sentence is quoted: tumor (2 papers); infection (1).